MACF1 (microtubule actin crosslinking factor 1)
Diseases named in the same sentence as MACF1 in open-access papers (continued):
Sharing a sentence is not in itself a finding about the gene and the disease.
osteoporosis (continued). "Our findings provide a new mechanism for understanding MSCs’ osteogenic differentiation and the regulation of bone formation, and highlight MACF1 as a potential therapeutic target for degenerative bone diseases such as osteoporosis." (PMID 32143362, 2020). "This proposes MACF1 as a key potential target for primary osteoporosis in the perspective of molecular medicine." (PMID 32143362, 2020). "Hopefully these findings will expand the biological scope of the MACF1 gene, and provide an experimental basis for targeting MACF1 in degenerative bone diseases such as osteoporosis." (PMID 32143362, 2020). "To verify the involvement of MACF1 in primary osteoporosis, we firstly analyzed the gene expression profile in human MSCs of elderly osteoporotic patients." (PMID 32143362, 2020). "Further analysis revealed that multiple osteogenic-related genes were negatively correlated with the degrees of osteoporosis, and MACF1 was positively correlated with these osteogenic-related genes." (PMID 32143362, 2020). "Nonetheless, it remains uncertain whether the downregulation of MACF1 during age‐related osteoporosis is responsible for the transition of β‐catenin from TCF‐ to FoxO‐ binding." (PMID 41363907, 2026). "Moreover, the therapeutic effect of MACF1 on ageing‐related osteoporosis and post‐menopausal osteoporosis was evaluated through in situ injection of the MACF1 overexpression plasmid." (PMID 34133068, 2021). "By coupling the results obtained, we have identified key roles of MACF1 in maintaining osteogenic differentiation and bone formation and advanced the potential for exploiting MACF1 as a new therapeutic target for degenerative bone diseases such as osteoporosis." (PMID 32143362, 2020). "Novel evidence showed that MACF1 is involved in diverse human diseases, including multiple neuronal diseases, congenital myasthenic syndrome, premature ovarian insufficiency, spectraplakinopathy, osteoporosis, proliferative diabetic retinopathy, and various types of cancer." (PMID 40244019, 2025). "In addition, the therapeutic treatment of aged mice with a pharmacological miR-138-5p inhibitor led to the significant elevation of MACF1 expression, which indicated that the inhibition of miR-138-5p alleviated senile osteoporosis by targeting the regulation of MACF1." (PMID 35982896, 2022). "We next investigated whether overexpression of MACF1 could rescue post‐menopausal osteoporosis." (PMID 34133068, 2021). "The results implied that MACF1 may relieve ageing‐related osteoporosis through inhibition of HES1." (PMID 34133068, 2021). "Moreover, the effect of MACF1 on post‐menopausal osteoporosis was also proved." (PMID 34133068, 2021). "However, as an important regulator for bone formation, few researchers have investigated the expression level of MACF1 during ageing process, and the relationships between MACF1 expression and ageing‐related osteoporosis still remain unclear." (PMID 34133068, 2021). "We have also found MACF1 negatively regulated HES1 expression and activities, which indicated a potential mechanism for MACF1 regulating ageing‐related osteoporosis." (PMID 34133068, 2021). "However, the relationship between MACF1 expression and ageing‐related osteoporosis remains unclear." (PMID 34133068, 2021). "All these results implied that MACF1 inhibited the expression level and activities of HES1, an osteogenic inhibiting factor in ageing‐related osteoporosis." (PMID 34133068, 2021). "We also previously identified that the target of miR-138-5p, microtubule actin cross-linking factor 1 (MACF1), could attenuate senile osteoporosis." (PMID 35982896, 2022). "We found that MACF1 expression was not impacted by ovariectomy, but enhancing MACF1 expression would still rescue bone formation in post‐menopausal osteoporosis." (PMID 34133068, 2021).
melanoma (5 papers, 2017 to 2025). A malignant, usually aggressive tumor composed of atypical, neoplastic melanocytes. "RTL1 overexpression activates the Wnt pathway by increasing the levels of DOCK4 and MACF1, both of which enhance the release of β-catenin from the destruction complex and increase the stability of β-catenin in melanoma cells." (PMID 38225934, 2024). "Another study presented data indicating that reduced MACF1 expression inhibited melanoma metastasis in mice by blocking the epithelial-to-mesenchymal transition process." (PMID 38609844, 2024). "Downregulation of MACF1 in B16F10 melanoma cells led to a decrease in cell proliferation which was confirmed in vivo with a decrease in tumor size compared to control cells." (PMID 33816492, 2021). "A study reported that MACF1 knockdown decreased the colony formation and invasion activities of B16F10 melanoma cells." (PMID 40244019, 2025). "Therefore, MACF1 could be a potential target for melanoma treatment." (PMID 38609844, 2024).
psychosis (5 papers, 2021 to 2025). "The results showed that a missense mutation (g.39914279 C>G; T-4642-S) in the MACF1 gene co-segregates with psychosis." (PMID 40244019, 2025). "In this sense, psychosis in the family can be explained by the presence of the variant g.39914279 C > G in MACF1 in combination with the two rare duplications, but this variant does not explain the psychosis phenotype of their distant relative BD-12." (PMID 33897758, 2021). "Both duplications need to co-segregate with other genetic factors to precipitate with psychosis, and the rare variant g.39914279 C > G of MACF1 is a good candidate." (PMID 33897758, 2021). "We identified a rare non-synonymous variant, g.39914279 C > G, in the MACF1 gene, segregating with psychosis." (PMID 33897758, 2021). "MACF1 interacts with the DISC1 (disrupted-in-schizophrenia 1) protein, reported as linked with psychosis." (PMID 35501310, 2022). "More research is needed to further elucidate the role of MACF1 in psychosis as well as its interaction with CNTN6 and CDH13." (PMID 33897758, 2021). "The role of MACF1 in cytoskeletal networks makes it an interesting candidate for psychosis." (PMID 33897758, 2021). "The participation of MACF1, together with its interplay with CNTN6 and CDH13 in psychosis needs to be further elucidated." (PMID 40244019, 2025). "Besides, our results confirm previous results suggesting the involvement of MACF1, CNTN6, and CDH13 in the etiology of psychosis." (PMID 33897758, 2021).
Lissencephaly (4 papers, 2019 to 2025). A spectrum of malformations of cortical development caused by insufficient neuronal migration that subsumes the terms agyria, pachygyria and subcortical band heterotopia. "Overall, MACF1 variants within the GAR domain demonstrate a strong genotype-phenotype correlation with lissencephaly with brain stem hypoplasia." (PMID 40666329, 2025). "Recently, highly penetrant de novo MACF1 mutations were identified in several patients with a newly characterized lissencephaly with a complex brain malformation." (PMID 31190668, 2019). "In contrast to the GAR domain’s strong correlation with lissencephaly and brainstem malformations, biallelic non-GAR domain MACF1 variants were linked to diverse developmental anomalies." (PMID 40666329, 2025).
Alzheimer disease (3 papers, 2012 to 2025). A progressive, neurodegenerative disease characterized by loss of function and death of nerve cells in several areas of the brain leading to loss of cognitive function such as memory and language. "By collecting these and other evidence, scientists proposed a hypothesis to explain the possible involvement of MACF1 in the pathogenesis of Alzheimer’s disease (AD)." (PMID 40244019, 2025). "Very recently, a new hypothesis has been proposed that involves MACF1 with Alzheimer’s disease." (PMID 32033020, 2020).
autism spectrum disorder (3 papers, 2021 to 2024). A spectrum of developmental disorders that includes autism, and Asperger syndrome. "Existing medical research shows that genetic mutations in the MACF1 gene have been associated with neurodevelopmental and neurodegenerative disorders, with variants of unknown significance also linked to autism spectrum disorder (ASD)." (PMID 39781307, 2024).
congenital myasthenic syndrome (3 papers, 2021 to 2025). Congenital myasthenic syndrome (CMS) is a group of genetic disorders of impaired neuromuscular transmission at the motor endplate characterized by fatigable muscle weakness. "Cluster 3 includes cases described in the literature with MACF1 variants associated with myasthenic syndrome, clustering with other congenital myasthenic syndrome phenotypes." (PMID 40666329, 2025). "MACF1 gene duplication (resulting in a decrease of MACF1 protein) is linked with a neuromuscular disease condition and MACF1 variants are associated with congenital myasthenia." (PMID 34448452, 2021).
endometrial cancer (3 papers, 2018 to 2022). Primary or metastatic malignant neoplasm involving the endometrium (mucous membrane that lines the endometrial cavity). "Moreover, we found that in endometrial carcinoma, the most frequently mutated gene, MACF1, also had a high lysine modification-related mutation rate in other cancers, including BLCA, LUSC, HNSC, and SKCM." (PMID 30065750, 2018). "A subsequent investigation using proteomics techniques identified MACF1 as a potential oncofetal biomarker that may be used for the diagnosis of colorectal cancer, while, most recently, whole-exome sequencing described MACF1 mutations in patients with endometrial cancer and renal cell carcinomas." (PMID 29373494, 2018). "The transcriptional complex of TEAD4 and AP-1 controls cell migration and invasion by regulating its downstream targets such as CDH2 (Cadherin 2) and MACF1 (Microtubule Actin Crosslinking Factor 1) in endometrial cancer and other cancers." (PMID 35602596, 2022).
epilepsy (3 papers, 2019 to 2025). A brain disorder characterized by episodes of abnormally increased neuronal discharge resulting in transient episodes of sensory or motor neurological dysfunction, or psychic dysfunction. "A recent study provides valuable insights by identifying the enrichment of MACF1 variants in epilepsy and their distinct localization." (PMID 40666329, 2025). "Notably, we observed variable expressivity and identified individuals with monoallelic variants, who presented with epilepsy, suggesting that MACF1-associated phenotypes have complex inheritance patterns." (PMID 40666329, 2025). "Genetic testing using the Blueprint Genetic’s 'Beyond Pediatric Epilepsy PLUS' panel revealed a missense mutation in the MACF1 gene, classified as a variant of unknown significance (VUS)." (PMID 39781307, 2024). "However, the number of reported autism disorder or epilepsy cases associated with MACF1 mutations remains limited." (PMID 39781307, 2024). "PRTG, TNC and MACF1 are candidate recessive epilepsy genes and our work highlights that inheritance of CH variants should not be excluded from gene discovery or diagnostic analyses of patients with epilepsy." (PMID 31190668, 2019). "Given both the enrichment in Epi4k probands for CH variants in these genes as well as their known involvement in neuronal processes, we suggest that PRTG, TNC and MACF1 are candidate recessive epilepsy genes." (PMID 31190668, 2019). "However, PRTG, TNC and MACF1 are potential novel recessive epilepsy genes and our results highlight that compound heterozygous variants should be considered in sporadic epilepsy." (PMID 31190668, 2019). "Her final diagnosis was epilepsy with generalized seizures of non-lesional origin, moderate cognitive impairment, pervasive developmental disorder, and a confirmed point mutation in the MACF1 gene." (PMID 39781307, 2024).
gastric cancer (3 papers, 2018 to 2025). A primary or metastatic malignant neoplasm involving the stomach. "MACF1 may serve as a marker of metastasis in gastric cancer." (PMID 41169522, 2025). "MACF1 expression may serve as a potential biomarker for stage IV gastric cancer." (PMID 41169522, 2025).
migraine (3 papers, 2022). "At the gene level, two genome-wide significant genes [MACF1 and THADA (thyroid adenoma associated)] were associated with migraine and T2D." (PMID 35627115, 2022).
type 2 diabetes (3 papers, 2013 to 2025). "The chromosome 1 MACF1‐HEYL signal region includes PABPC4 which has been implicated in type 2 diabetes through an effect mediated through visceral adipose tissue." (PMID 40538118, 2025). "Another example is a predicted SAV in the MACF1 gene (NM_012090.4: c.6868A > G; NP_036222.3: p.M2290V), which has been reported in association with type 2 diabetes." (PMID 24451234, 2014). "The variants N939D in COBLL1 and M2290V in MACF1 were associated with type 2 diabetes, yet non-coding SNPs in these loci have previously been associated with other metabolic phenotypes." (PMID 23160641, 2013). "The M2290V variant in MACF1 was shown to increase the risk of type 2 diabetes and subsequent analyses of related metabolic phenotypes showed that the same allele also decreased fasting serum HDL-cholesterol levels." (PMID 23160641, 2013). "We identified a low-frequency amino-acid polymorphism in CD300LG associated with fasting HDL-cholesterol and two common amino-acid polymorphisms in COBLL1 and MACF1 associated with type 2 diabetes." (PMID 23160641, 2013). "A low-frequency (MAF 3.5%) non-synonymous (R82C) polymorphism in CD300LG was associated with lower fasting levels of serum HDL-cholesterol while two common (MAF 12.5% and 23.4%, respectively) non-synonymous polymorphisms in COBLL1 and MACF1 were associated with type 2 diabetes." (PMID 23160641, 2013).
autism (2 papers, 2019 to 2025). Persistent deficits in social interaction and communication and interaction as well as a markedly restricted repertoire of activity and interest as well as repetitive patterns of behavior. "MACF1 is considered a risk gene for autism (SFARI) and serves two functions in vesicular traffic, namely anterograde Golgi-associated transit and Golgi to plasma membrane trafficking." (PMID 40779003, 2025). "Microtubule-actin crosslinking factor 1 (MACF1) isoform 1 was downregulated in adults with autism." (PMID 40779003, 2025).
Brain malformations (2 papers, 2021 to 2024). "These included enhancers linked to the disease genes MACF1 (OMIM #618325) and TUBB2A (OMIM #615763), of which coding pathogenic mutations cause brain malformations, and C12orf4 (OMIM #618221) of which bi-allelic variants cause intellectual disability." (PMID 34663447, 2021).
colitis (2 papers, 2017 to 2021). Inflammation of the colon. "However, the molecular connection between MACF1 and the tight junctions, as well as the MT-dependent mechanism responsible for tight junction dynamics and how these processes are related to colitis remains unclear." (PMID 33816492, 2021). "At the cellular level, the absence of MACF1 decreased the tight junction dynamics associated with wound healing defects in intestinal epithelium, which increased the susceptibility of the conditional knockout mice to experimental colitis." (PMID 33816492, 2021).
colon cancers (2 papers, 2014 to 2022). "Based on this, the increased inclusion of the alternative exon in MACF1 transcripts was proposed to contribute to altered Wnt signaling in the lung and colon cancers, and our result expands this supposition to the bladder cancer." (PMID 24622401, 2014).
colorectal cancer (2 papers, 2015 to 2018). A primary or metastatic malignant neoplasm that affects the colon or rectum. "Besides the APC gene, which occurs in over two-thirds of colorectal cancer, WNT2 and MACF1 also impact the Wnt pathway, while RASA1 is in the RAS pathway." (PMID 25974029, 2015).
COVID-19 (2 papers, 2022 to 2024). A disease caused by infection with severe acute respiratory syndrome coronavirus 2. "In addition, we deployed validation experiments for local splicing changes of 6 genes (CD74, LRRFIP1, SH3GLB1, MACF1, RPS24 and PDLIM5) between 9 COVID-19 cases and 10 controls by semiquantitative reverse transcription (RT)-PCR." (PMID 35421082, 2022).
glioma (2 papers, 2021 to 2025). A benign or malignant brain and spinal cord tumor that arises from glial cells (astrocytes, oligodendrocytes, ependymal cells). "In the BrM/Glioma group, 8 DEPs (PRL, SNCA, MACF1, ACAT2, VWF, GSN, FCGBP, and F10) were selected for ROC curve analysis based on a logistic regression model." (PMID 39716938, 2025).
heart failure (2 papers, 2013 to 2015). Inability of the heart to pump blood at an adequate rate to meet tissue metabolic requirements. "Western analysis of ventricular lysates from control wild type mice or mice with TAC induced heart failure revealed that MACF1 expression was low under basal conditions, but increased nearly 2.5 fold in mice exposed to TAC." (PMID 24086300, 2013).
Hypertension (2 papers, 2018 to 2022). The presence of chronic increased pressure in the systemic arterial system. "It is worth mentioning that GWAS has found MACF1 to be associated with vascular diseases like hypertension and peripheral artery disease, further supporting the idea that headaches may somehow be linked to the vascular system." (PMID 35627115, 2022).
liver cancer (2 papers, 2015 to 2021). An epithelial or non-epithelial malignant neoplasm that arises from the liver. "When HepG2 cells were transfected with the gene coding for hepatitis B protein X, the levels of the MACF1 protein varied, suggesting that MACF1 might play an important role in occurrence of liver cancer." (PMID 34621291, 2021).
lung adenocarcinoma (2 papers, 2013 to 2020). A carcinoma that arises from the lung and is characterized by the presence of malignant glandular epithelial cells. "Furthermore, tyrosyl-tRNA synthetase (TyrRS) and microtubule-actin crosslinking factor 1 (MACF-1) were at higher abundance in lung adenocarcinoma tissues than adjacent normal tissues." (PMID 33330488, 2020). "We have discovered ATP6V1C1, MYBBP1A, MACF1 and MYO10 upregulation in lung adenocarcinoma and accordingly, it is concluded that these genes have an important role in lung adenocarcinoma metastasis and we have reported all the mentioned genes for the first time in lung adenocarcinoma." (PMID 23874428, 2013).
lung carcinoma (2 papers, 2018 to 2022). "Further experiments directly validated the high level of MACF1 in several lung cancers, and the knockdown of MACF1 inhibited the reproductivity of solid tumors." (PMID 29587367, 2018). "Similarly, changes in AS events in lung cancer will also affect the transcripts of VEGFA, MACF1, APP, and NUMB genes, thereby promoting the process of tumorigenesis." (PMID 36466711, 2022).
metabolic syndrome (2 papers, 2020 to 2022). A cluster of metabolic risk factors for CARDIOVASCULAR DISEASES and TYPE 2 DIABETES MELLITUS. "It has been shown that the MACF1 gene is associated with metabolic syndrome and inflammation." (PMID 36672824, 2022).
psoriasis (2 papers, 2024 to 2025). An autoimmune condition characterized by red, well-delineated plaques with silvery scales that are usually on the extensor surfaces and scalp. "Calculation of a plakin gene module score, comprising Dsp, Dst, Eppk1, Evpl, Macf1, Plec, and Ppl, revealed a broad reduction in the IMQ-treated condition, partially recapitulating the findings observed in human lesional psoriasis." (PMID 40746860, 2025).
sarcoma (2 papers, 2023 to 2024). A usually aggressive malignant neoplasm of the soft tissue or bone. "Interestingly, cytoskeleton proteins, including RASA1, RASAL2, NCKAP5, MACF1 and ARHGAP24, were reduced following differentiation, indicating that the sarcoma microenvironment induces resident‐like myeloid cell transfer." (PMID 39658531, 2024). "Although the expression of CNTNAP4 in this dataset had lowly expressed transcripts, the levels of CNTNAP4 interacting genes (MACF1, MLLT4, FBXO21, CASK) were found to be highly enriched in the Ki67high sarcoma cells, which was found as well to cluster with high MDM2 expression." (PMID 36599925, 2023).